IL27 (interleukin 27)
Description:
Associates with EBI3 to form the IL-27 interleukin, a heterodimeric cytokine which functions in innate immunity. IL-27 has pro- and anti-inflammatory properties, that can regulate T-helper cell development, suppress T-cell proliferation, stimulate cytotoxic T-cell activity, induce isotype switching in B-cells, and that has diverse effects on innate immune cells. Among its target cells are CD4 T-helper cells which can differentiate in type 1 effector cells (TH1), type 2 effector cells (TH2) and IL17 producing helper T-cells (TH17). It drives rapid clonal expansion of naive but not memory CD4 T-cells. It also strongly synergizes with IL-12 to trigger interferon-gamma/IFN-gamma production of naive CD4 T-cells, binds to the cytokine receptor WSX-1/TCCR which appears to be required but not sufficient for IL-27-mediated signal transduction. IL-27 potentiate the early phase of TH1 response and suppress TH2 and TH17 differentiation. It induces the differentiation of TH1 cells via two distinct pathways, p38 MAPK/TBX21- and ICAM1/ITGAL/ERK-dependent pathways. It also induces STAT1, STAT3, STAT4 and STAT5 phosphorylation and activates TBX21/T-Bet via STAT1 with resulting IL12RB2 up-regulation, an event crucial to TH1 cell commitment. It suppresses the expression of GATA3, the inhibitor TH1 cells development. In CD8 T-cells, it activates STATs as well as GZMB. IL-27 reveals to be a potent inhibitor of TH17 cell development and of IL-17 production. Indeed IL27 alone is also able to inhibit the production of IL17 by CD4 and CD8 T-cells. While IL-27 suppressed the development of pro-inflammatory Th17 cells via STAT1, it inhibits the development of anti-inflammatory inducible regulatory T-cells, iTreg, independently of STAT1. IL-27 also has an effect on cytokine production, it suppresses pro-inflammatory cytokine production such as IL2, IL4, IL5 and IL6 and activates suppressors of cytokine signaling such as SOCS1 and SOCS3. Apart from suppression of cytokine production, IL-27 also antagonizes the effects of some cytokines such as IL6 through direct effects on T-cells. Another important role of IL-27 is its antitumor activity as well as its antiangiogenic activity with activation of production of antiangiogenic chemokines such as IP-10/CXCL10 and MIG/CXCL9. In vein endothelial cells, it induces IRF1/interferon regulatory factor 1 and increase the expression of MHC class II transactivator/CIITA with resulting up-regulation of major histocompatibility complex class II. IL-27 also demonstrates antiviral activity with inhibitory properties on HIV-1 replication.
Synonyms: IL27A; IL30; IL-27; p28; IL27p28; IL-27A; MGC71873
Tractability: Antibody: UniProt places it where antibodies can reach, with high confidence; its Gene Ontology location is reachable by antibodies, with high confidence; UniProt predicts a signal peptide or a membrane-spanning region.
Gene: Protein-coding gene on chromosome 16 (28,499,362 to 28,512,051, reverse strand). Ensembl gene ENSG00000197272.
Subcellular location: Secreted
Pathways (Reactome):
Immune System: Interleukin-27 signaling
Gene Ontology:
Molecular function: protein binding; interleukin-27 receptor binding; signaling receptor binding
Biological process: positive regulation of type II interferon production; regulation of T cell proliferation; regulation of T-helper 1 cell differentiation; cell surface receptor signaling pathway via JAK-STAT; interleukin-27-mediated signaling pathway; negative regulation of apoptotic process; positive regulation of interleukin-10 production; positive regulation of MAPK cascade; response to bacterium; response to Gram-positive bacterium
Cellular component: extracellular region; receptor complex; cytosol; endoplasmic reticulum lumen; cell surface
Genetic constraint (gnomAD): Loss-of-function variants: 11 observed, 25.92 expected, observed/expected ratio (o/e) 0.42, 90% interval 0.27 to 0.7. The upper end of that interval is the gene's LOEUF score, 0.7, which puts it in group 2 of 6, group 1 being the genes least tolerant of losing a copy. Missense variants: 299 observed, 314.83 expected, observed/expected ratio (o/e) 0.95, 90% interval 0.86 to 1.04. Synonymous variants: 134 observed, 143.06 expected, observed/expected ratio (o/e) 0.94, 90% interval 0.81 to 1.08.
Homologues: Orthologues: macaque IL27 (89% identical), chimpanzee IL27 (73% identical), mouse Il27 (72% identical), pig IL27 (72% identical), guinea pig IL27 (71% identical), dog IL27 (70% identical), rat Il27 (69% identical).
Diseases named in the same sentence as IL27 in open-access papers:
IL27 is named in the same sentence as 353 diseases in open-access papers, as found by Europe PMC text mining. Sharing a sentence is not in itself a finding about the gene and the disease. The quoted sentences say what the papers report.
autoimmune disease (69 papers, 2008 to 2025). A disorder resulting from loss of function or tissue destruction of an organ or multiple organs, arising from humoral or cellular immune responses of the individual to their own tissue constituents. "IL-27 has been implicated in the immune pathogenesis of MS and is a potential therapeutic target in CNS autoimmune diseases." (PMID 39766196, 2024). "IL-5, IL-9, IL-10, IL-23, and IL-27 are also related to the Th2 response (T-cell response associated with allergies, progressive systemic sclerosis, and autoimmune disorders)." (PMID 36439158, 2022). "IL-27-A964G and IL-27-T4730C were associated with digestive and gynecological neoplasms and with other autoimmune diseases such as Behcet disease (BD), ulcerative colitis (UC) and rheumatoid arthritis (RA)." (PMID 35011777, 2021). "IL-27 has been implicated in the pathologies of several autoimmune diseases, such as multiple sclerosis, systemic lupus erythematosus, rheumatoid arthritis, autoimmune gastritis and inflammatory bowel disease." (PMID 31949260, 2020). "The dual role of IL-27 is related to the different tissues involved, the underlying mechanism, or the kind and stage of autoimmune diseases." (PMID 32616337, 2020). "To determine if IL-27 or IL-30 can be used as a potential therapeutic for autoimmune diseases, we generated recombinant adeno-associated virus that express IL-27 (AAV-IL-27) or IL-30 (AAV-IL-30) and the control AAV virus (AAV-ctrl)." (PMID 29740452, 2018). "A previous study associated IL27 with different autoimmune diseases." (PMID 37175481, 2023). "IL-27 (IL-27p28/Ebi3) and IL-35 (IL-12p35/Ebi3) are immunosuppressive cytokines produced by myeloid and lymphoid cells and have been implicated in the suppression of autoimmune diseases." (PMID 35897732, 2022). "Mutations in IL-27 could be a causal effect for some autoimmune diseases such as IBD, chronic obstructive pulmonary disease, and asthma." (PMID 31835347, 2019). "Although IL-12 family members IL-12, IL-23, IL-27 and IL-35, serve as important players in association with autoimmune diseases 26,27, their roles in SS remain largely unknown." (PMID 31754394, 2019). "Moreover, the depletion of Treg cells adds additional risk for IL-27-based therapy of autoimmune diseases like MS." (PMID 29740452, 2018). "The role of IL-27 has been studied, but the underlying mechanism of IL-27 in autoimmune disease, specifically SjS, is still unknown." (PMID 22827855, 2012). "Interestingly, a different immunological profile appeared to characterize the two diagnoses, as CC-chemokine 20 and interleukin 27 (IL27) as well as autoimmune diseases PRSs were negatively associated with PPD in the BD model but did not significantly contribute to the MDD model." (PMID 39766785, 2024). "Notably, the polymorphism in the IL-27 gene could regulate host innate and adaptive immune response and was associated with infectious diseases, autoimmune diseases, and caner." (PMID 38690286, 2024). "Inhibition of iOPN expression mediated by Type-I IFN receptor (IFNAR) expressed by DCs de-repressed interleukin-27 (IL-27) secretion, and as a result, prevented Th17 responses in vitro and in vivo, which, when aberrantly expressed, has been associated to the generation of autoimmune diseases." (PMID 36769264, 2023). "In conclusion, this study revealed that IL-27 is a critical modulator of MSC immune plasticity and presented a novel therapeutic strategy utilizing IL-27-enhanced MSC2 for autoimmune diseases." (PMID 40642057, 2025). "Recently research examined the role of interleukin 27 (IL-27) that triggers Tr1 cells, which suppress the responses of Th2 and Th17 cells, which reduce the intensity of autoimmune diseases." (PMID 38850409, 2024). "The purpose of this review is to briefly discuss the structure and function of IL-27 and highlight recent advances focusing on the roles of IL-27 in the pathogenesis of autoimmune diseases." (PMID 39766196, 2024).
autoimmune disease (continued). "This updated advancement of bifunctional IL-27 in autoimmune disorders is summarized in both human and animal model studies." (PMID 38566992, 2024). "It is hoped that, in the future, more precise methods to targeting abnormally expressed IL-27 will bring potential for inhibiting autoimmune disease pathogenesis." (PMID 38566992, 2024). "Further research is essential to fully understand IL-27’s mechanisms of action and therapeutic potential in autoimmune diseases." (PMID 39766196, 2024). "Its pleiotropic functions make IL-27 an intriguing target for therapeutic intervention in various immune-mediated diseases, ranging from autoimmune disorders to cancer." (PMID 39766196, 2024). "The IL-12 family, comprising IL-12, IL-23, IL-27, and IL-35, plays a regulatory role in the immune system’s ability to combat infectious diseases, autoimmune diseases, and tumors." (PMID 37464360, 2023). "Mice overexpressing the Il27p28 gene are resistant to autoimmune diseases, and it was proposed that such resistance originates from IL-27’s ability to antagonize inflammatory T cell responses, particularly Th1 and Th17 immunity." (PMID 36725904, 2023). "For example, Asian-specific haQTLs provided novel candidate variants in gene loci associated with leprosy (SIGLEC5, TNFSF15) and autoimmune disease (CARD9, IRF5, IL27, FOS) (nd 48)." (PMID 35102304, 2022). "Accordingly, previous studies that investigated serum IL-27 levels in autoimmune diseases reported that serum IL-27 is increased in patients with rheumatoid arthritis, systemic lupus erythematosus, and systemic sclerosis compared to those in healthy subjects." (PMID 34335091, 2021). "Regarding other autoimmune diseases, IL-27 reduction has been reported in multiple sclerosis (MS) patients." (PMID 34033291, 2021). "IL-27 has been demonstrated to suppress human Th17 cells and promote human Tr1 cells, suggesting the important role of IL-27 in regulating human autoimmune diseases." (PMID 34299138, 2021). "The immune regulation of two cytokines related to IL-12 family, namely IL-27 and IL-35, has been demonstrated in several autoimmune diseases." (PMID 34033291, 2021). "Previous studies confirmed the important role of IL-27 in the induction of IL-10-producing Tr1 cells to resolve autoimmune diseases, especially in EAE." (PMID 34299138, 2021). "Interleukin 27 has been shown to attenuate multiple autoimmune disorders by regulating the response of T cells and decreasing the production of inflammatory cytokines." (PMID 32849596, 2020). "Interleukin 27 (IL-27) plays diverse immune regulatory roles in autoimmune disorders and promotes the generation of IL-10–producing CD4+ T cells characterized by producing the immunosuppressive cytokine IL-10." (PMID 32849596, 2020). "The anti-inflammatory properties of IL-27 have been reported in several autoimmune diseases, and IL-27 has been proposed as a therapy to modify inflammatory conditions by regulating T-cell responses." (PMID 32849596, 2020). "IL-27 activates multiple signaling cascades and has both anti- and proinflammatory activities in different autoimmune diseases." (PMID 31949260, 2020). "Several recent reports showed that IL-27 can induce the production of IgG1 by B cells and support antibody-driven autoimmune disease." (PMID 31198792, 2019). "IL-27 has been reported to have pro- and anti-inflammatory activities in a variety of autoimmune diseases." (PMID 31754394, 2019). "The use of exogenous IL-27 has been recognized as a novel biological tool to treat a vast range of inflammatory and autoimmune disease." (PMID 32047492, 2019). "More importantly, IL-27 has been evidenced to support antibody-driven autoimmune diseases through both direct and indirect effects on B cells, whereas another report revealed that IL-27 can directly inhibit the growth of leukemic B cells." (PMID 31198792, 2019).
autoimmune disease (continued). "Our data reveal a new cellular regulatory mechanism of IL-27 that targets DC-mediated immune responses in autoimmune diseases such as multiple sclerosis (MS) and experimental autoimmune encephalomyelitis (EAE)." (PMID 30483251, 2018). "Interleukin-27 (IL-27) and its subunit P28 (also known as IL-30) have been shown to inhibit autoimmunity and have been suggested as potential immunotherapeutic for autoimmune diseases such as multiple sclerosis (MS)." (PMID 29740452, 2018). "Macrophages and dendritic cells are the main sources of IL-27 production during infectious and autoimmune diseases." (PMID 29033934, 2017). "IL-27 exerts inhibitory effect on formation and functioning of ectopic GC in animal models of autoimmune diseases including SLE and RA." (PMID 29387055, 2017). "IL-27 has been found to possess pro- and anti-inflammatory activity and play an essential role during the pathogenesis of infectious and autoimmune diseases, but its functions in chronic inflammatory disease remain controversial." (PMID 27994590, 2016). "IL-27 has been thoroughly investigated in several autoimmune disorders, such as inflammatory bowel disease, rheumatoid arthritis (RA), experimental autoimmune encephalitis (EAE), psoriasis, and Sjögren’s syndrome (SS)." (PMID 26872212, 2016). "The pro-inflammatory capacity of IL-27 has been described in several autoimmune disorders, such as RA, EAE, psoriasis, and SS." (PMID 26872212, 2016). "As mentioned, down-regulationof Th17 or IL-17 can be an effective therapyfor treatment of many autoimmune diseases.Previous studies have confirmed that IL-27 is astrong suppressor of Th17 and IL-17." (PMID 24611150, 2014). "In this regard, the importance of IL-19, IL-27, and IL-35 in infections such as TB and in autoimmune diseases is under investigation." (PMID 22666281, 2012). "IL-27 is produced mostly by innate immune cells and to induce suppressive effects on Th1, Th2, and Th17 cell responses in various infection and autoimmune disease models." (PMID 20126401, 2010). "These pieces of evidence suggest the powerful regulatory potential of IL-27 in autoimmune diseases." (PMID 41362621, 2025). "Thus, vaccines containing adjuvants that induce IL-12 and IL-23 would be more effective in preventing infectious diseases while IL-27 and IL-35 suppress autoimmune diseases." (PMID 40114923, 2025). "IL-27 exhibits dual effects on inflammatory response in autoimmune disease." (PMID 41362621, 2025). "Here we discuss the roles B cells play in suppressing CNS autoimmune diseases with a particular focus on IL-27-producing and IL-35-producing regulatory B cells (Bregs) and IL-35 containing exosomes (i35-exosomes) and IL-27-exosomes (i27-exosomes) that they secrete." (PMID 40114923, 2025). "Another important area of research on IL-27 is autoimmunity and autoimmune diseases." (PMID 39063193, 2024). "Moreover, evidence based on the association of IL-27 with inflammatory autoimmune diseases indicated that IL-27 not only inhibits autoimmunity development but also promotes autoimmune disease pathogenesis." (PMID 38566992, 2024). "Additionally, it explores the involvement of IL-27 in autoimmune diseases, such as multiple sclerosis (MS) and rheumatoid arthritis (RA), offering insights into its potential therapeutic implications." (PMID 39766196, 2024). "Consequently, both features of IL-27 have been exploited to promote anti-tumor responses and for treatment of autoimmune diseases." (PMID 37334383, 2023). "Since dysregulation of IL-10 is associated with an increased risk of developing many autoimmune diseases, the ability of this system to correct the functionality of IL-27 and subsequent IL-10 expression levels is a promising therapeutic approach to treat several autoimmune diseases." (PMID 36009412, 2022).